RNU6-440P (RNA, U6 small nuclear 440, pseudogene)
Gene: Small nuclear RNA gene on chromosome 2 (201,927,439 to 201,927,543, forward strand). Ensembl gene ENSG00000212184.
Homologues: Orthologues: chimpanzee U6 (96% identical), macaque U6 (92% identical), pig U6 (76% identical), dog U6 (74% identical), dog U6 (69% identical), guinea pig U6 (65% identical). Paralogues in human: RNU6-41P (82% identical), RNU6-517P (82% identical), RNU6-891P (82% identical), RNU6-1060P (81% identical), RNU6-116P (81% identical), RNU6-393P (81% identical), RNU6-698P (81% identical), RNU6-1075P (80% identical), RNU6-10P (80% identical), RNU6-12P (80% identical), RNU6-1303P (80% identical), RNU6-13P (80% identical), and 1286 more.